MXD4 (MAX dimerization protein 4)
Description:
Transcriptional repressor. Binds with MAX to form a sequence-specific DNA-binding protein complex which recognizes the core sequence 5'-CAC[GA]TG-3'. Antagonizes MYC transcriptional activity by competing for MAX and suppresses MYC dependent cell transformation (By similarity).
Synonyms: bHLHc12; MAD4; MSTP149; MST149
Tractability: PROTAC: ubiquitination databases record sites on it.
Gene: Protein-coding gene on chromosome 4 (2,247,432 to 2,262,115, reverse strand). Ensembl gene ENSG00000123933.
Subcellular location: Nucleus
Subcellular location (Human Protein Atlas): Cytosol
Pathways (Reactome):
Signal Transduction: Nuclear signaling by ERBB4
Gene Ontology:
Molecular function: protein binding; DNA-binding transcription factor activity, RNA polymerase II-specific; RNA polymerase II cis-regulatory region sequence-specific DNA binding; protein dimerization activity
Biological process: negative regulation of transcription by RNA polymerase II; regulation of transcription by RNA polymerase II
Cellular component: cytosol; chromatin; nucleoplasm; nucleus; RNA polymerase II transcription repressor complex
Genetic constraint (gnomAD): Loss-of-function variants: 16 observed, 17.74 expected, observed/expected ratio (o/e) 0.9, 90% interval 0.61 to 1.37. The synonymous counts are far from expectation, so gnomAD's model fits this gene poorly and the ratio says little. Missense variants: 301 observed, 256.58 expected, observed/expected ratio (o/e) 1.17, 90% interval 1.07 to 1.29. Synonymous variants: 164 observed, 119.52 expected, observed/expected ratio (o/e) 1.37, 90% interval 1.21 to 1.56.
Homologues: Orthologues: chimpanzee MXD4 (100% identical), macaque MXD4 (99% identical), dog MXD4 (92% identical), pig MXD4 (92% identical), guinea pig MXD4 (92% identical), mouse Mxd4 (92% identical), rabbit MXD4 (91% identical), rat Mxd4 (88% identical), zebrafish mxd4 (76% identical), tropical clawed frog mxd4 (60% identical), Caenorhabditis elegans mdl-1 (33% identical). Paralogues in human: MXD1 (53% identical), MXI1 (53% identical), MXD3 (44% identical), MNT (28% identical).
Diseases named in the same sentence as MXD4 in open-access papers:
MXD4 is named in the same sentence as 21 diseases in open-access papers, as found by Europe PMC text mining. Sharing a sentence is not in itself a finding about the gene and the disease. The quoted sentences say what the papers report.
leukemia (3 papers, 2022 to 2025). A malignant (clonal) hematologic disorder, involving hematopoietic stem cells and characterized by the presence of primitive or atypical myeloid or lymphoid cells in the bone marrow and the blood. "In this study, we showed that deletion of UHRF1 significantly prolongs the survival time of the mice with AML by targeting the self-renewal of leukemia initiating cells through SAP30-mediated MXD4 activation." (PMID 36302855, 2022). "Previous studies have found that in myeloid leukemia, targeting MXD4 can eliminate leukemia-initiating cells, and KAT7 expression is elevated in leukemia cells." (PMID 40612663, 2025).
cutaneous melanoma (1 paper, 2022). A primary melanoma arising from atypical melanocytes in the skin. "In the cutaneous melanoma cell lines, MEL 04.01 and MEL 06.24, Nutlin-3 treatment increased significantly CDKN1A, CYFIP2 and PTCHD4 expression, whereas PIK3IP1 and MXD4 levels do not or hardly change." (PMID 36139642, 2022).
gastric cancer (1 paper, 2023). A primary or metastatic malignant neoplasm involving the stomach. "In gastric cancer, both CASTOR2 and MXD4 expression levels were inversely correlated with MYEOV expression levels." (PMID 36698109, 2023).
lung adenocarcinoma (1 paper, 2023). A carcinoma that arises from the lung and is characterized by the presence of malignant glandular epithelial cells. "An inverse correlation between MYEOV and MXD4 expression levels was also observed in lung adenocarcinomas." (PMID 36698109, 2023).
pancreatic cancer (1 paper, 2023). "Therefore, repression of MXD4 expression by MYEOV may facilitate the malignant transformation of pancreatic cancer through activation of c-Myc and other proteins." (PMID 36698109, 2023). "Conversely, in pancreatic cancer cells, MYEOV expression is upregulated and promotes the downregulation of MXD4 and CASTOR2, resulting in the activation of c-Myc and mTORC1 and tumor progression." (PMID 36698109, 2023).
uveal melanoma (1 paper, 2022). A melanoma derived from melanocytes of the uveal tract. "Nutlin-3 treatment of the uveal melanoma cell line 92.1 showed transcriptional regulation of these genes similar to the results in MEL202 with the exception of MXD4, which is not affected." (PMID 36139642, 2022).
tumor (7 papers, 2013 to 2023). "For example, 11 of the 14 tumor types (78.6%) expressing the highest levels of Mxd4 are associated with more prolonged survival, whereas in the case of Mxd3 this is true for only 5 of 17 tumor types (29.4%) in the case of Mxd3." (PMID 35203395, 2022). "Despite the evidence implicating Mxd4 in the induction and/or maintenance of cell quiescence, there is little published information regarding a similar role in human neoplasia." (PMID 35203395, 2022). "MXD4 is a MAD family protein and putative tumor suppressor that, through heterodimerization with MAX, antagonizes MYC and downstream gene regulatory activities." (PMID 37894362, 2023).
cancer (5 papers, 2013 to 2025). A tumor composed of atypical neoplastic, often pleomorphic cells that invade other tissues. "This is mostly driven by the cancer-related TF MAX whose binding is antagonized by many other bHLH TFs such as MNT, MXD1, and MXD4." (PMID 39013578, 2024). "Antithetical to ZNF131, MXD4 was identified as the strongest negative TF correlate of POLR3G expression in cancer and, we show, is a negative determinant of POLR3G mRNA abundance." (PMID 37894362, 2023). "ZNF131, for example, is the strongest DNA-binding transcription factor positively linked with POLR3G mRNA abundance in cancer, whereas MAX-dimerization protein 4 (MXD4) is the strongest negative correlate." (PMID 37894362, 2023).
infection (1 paper, 2023). The state of being infected such as from the introduction of a foreign agent such as serum, vaccine, antigenic substance or organism. "As we analyze the TFs that belongs to each time of infection evaluated, we found that at 24-hpi, more than half of TFs are related to an M1 phenotype in humans and mouse, and also were upregulated in our results, corresponding to ARID3A, IRF1, MXD4, and BNC1." (PMID 38162669, 2023).
MXD4 also shares sentences with these, for which no sentence is quoted: myeloid leukemia (3 papers); colon cancer (2); brain neoplasm (1); glioblastoma (1); medulloblastoma (1); myeloid malignancies (1); myeloproliferative disease (1); myxoid chondrosarcoma (1); sarcoma (1); schizophrenia (1); T-cell lymphoma (1); T-lymphomas (1).